RN7SKP212 (RN7SK pseudogene 212)
Gene: Miscellaneous RNA gene on chromosome 3 (130,811,768 to 130,812,095, reverse strand). Ensembl gene ENSG00000222783.
Homologues: Orthologues: chimpanzee 7SK (99% identical), mouse Gm55969 (49% identical). Paralogues in human: RN7SKP217 (66% identical), RN7SKP79 (66% identical), RN7SKP90 (66% identical), RN7SKP162 (65% identical), RN7SKP202 (65% identical), RN7SKP257 (65% identical), RN7SKP250 (65% identical), RN7SKP255 (65% identical), RN7SKP71 (65% identical), 7SK (64% identical), RN7SKP163 (64% identical), RN7SKP180 (64% identical), and 284 more.